ATP5MJ (ATP synthase membrane subunit j)
Description:
Subunit j, of the mitochondrial membrane ATP synthase complex (F(1)F(0) ATP synthase or Complex V) that produces ATP from ADP in the presence of a proton gradient across the membrane which is generated by electron transport complexes of the respiratory chain. ATP synthase complex consist of a soluble F(1) head domain - the catalytic core - and a membrane F(1) domain - the membrane proton channel. These two domains are linked by a central stalk rotating inside the F(1) region and a stationary peripheral stalk. During catalysis, ATP synthesis in the catalytic domain of F(1) is coupled via a rotary mechanism of the central stalk subunits to proton translocation (Probable). In vivo, can only synthesize ATP although its ATP hydrolase activity can be activated artificially in vitro (By similarity). Part of the complex F(0) domain. Minor subunit required to maintain the ATP synthase population in the mitochondria.
Synonyms: MLQ; ATP5MPL; C14orf2; MP68; 6.8PL; PLPM
Tractability: Small molecule: a structure with a bound ligand is known. Antibody: UniProt predicts a signal peptide or a membrane-spanning region. PROTAC: ubiquitination databases record sites on it.
Gene: Protein-coding gene on chromosome 14 (103,912,281 to 103,928,269, reverse strand). Ensembl gene ENSG00000156411.
Subcellular location: Mitochondrion membrane
Subcellular location (Human Protein Atlas): Mitochondria; Nucleoli fibrillar center
Pathways (Reactome):
Metabolism: Formation of ATP by chemiosmotic coupling
Organelle biogenesis and maintenance: Cristae formation
Gene Ontology:
Biological process: proton motive force-driven ATP synthesis
Cellular component: mitochondrial membrane; mitochondrion; mitochondrial inner membrane; proton-transporting ATP synthase complex
Genetic constraint (gnomAD): Loss-of-function variants: 4 observed, 9.86 expected, observed/expected ratio (o/e) 0.41, 90% interval 0.2 to 0.93. That is too few expected variants to judge how well the gene tolerates losing a copy. Missense variants: 66 observed, 75.71 expected, observed/expected ratio (o/e) 0.87, 90% interval 0.71 to 1.07. Synonymous variants: 23 observed, 22.39 expected, observed/expected ratio (o/e) 1.03, 90% interval 0.74 to 1.46.
Homologues: Orthologues: macaque ATP5MJ (84% identical), chimpanzee ATP5MJ (78% identical), rat Atp5mj-ps1 (76% identical), rat Atp5mpl (76% identical), mouse Atp5mj (72% identical), dog ATP5MJ (67% identical), rat Atp5mpl (67% identical).
Diseases named in the same sentence as ATP5MJ in open-access papers:
ATP5MJ is named in the same sentence as 3 diseases in open-access papers, as found by Europe PMC text mining. Sharing a sentence is not in itself a finding about the gene and the disease.
ATP5MJ shares sentences with these, for which no sentence is quoted: tumor (3 papers); cancer (1); lung carcinoma (1).